CCDC137 (coiled-coil domain containing 137)
Synonyms: MGC16597; RaRF
Tractability: PROTAC: ubiquitination databases record sites on it; its protein half-life has been measured.
Gene: Protein-coding gene on chromosome 17 (81,666,737 to 81,673,904, forward strand). Ensembl gene ENSG00000185298.
Subcellular location: Chromosome
Subcellular location (Human Protein Atlas): Nucleoli; Mitotic chromosome; Nucleoplasm
Gene Ontology:
Molecular function: protein binding; RNA binding
Cellular component: chromosome; nucleolus; nucleoplasm; nucleus
Genetic constraint (gnomAD): Loss-of-function variants: 22 observed, 24.02 expected, observed/expected ratio (o/e) 0.92, 90% interval 0.65 to 1.31. The synonymous counts are far from expectation, so gnomAD's model fits this gene poorly and the ratio says little. Missense variants: 388 observed, 301.31 expected, observed/expected ratio (o/e) 1.29, 90% interval 1.18 to 1.4. Synonymous variants: 162 observed, 116.18 expected, observed/expected ratio (o/e) 1.39, 90% interval 1.23 to 1.59.
Homologues: Orthologues: chimpanzee CCDC137 (98% identical), macaque CCDC137 (92% identical), pig CCDC137 (74% identical), mouse Ccdc137 (70% identical), guinea pig CCDC137 (68% identical), dog CCDC137 (67% identical), rat Ccdc137 (57% identical), tropical clawed frog CCDC137 (38% identical), zebrafish ccdc137 (32% identical), Drosophila melanogaster CG8326 (25% identical).
Diseases named in the same sentence as CCDC137 in open-access papers:
CCDC137 is named in the same sentence as 14 diseases in open-access papers, as found by Europe PMC text mining. Sharing a sentence is not in itself a finding about the gene and the disease. The quoted sentences say what the papers report.
glioma (3 papers, 2021 to 2023). A benign or malignant brain and spinal cord tumor that arises from glial cells (astrocytes, oligodendrocytes, ependymal cells). "CCDC137 expression was positively correlated with tumor associated macrophages (TAMs) and cancer associated fibroblasts (CAFs) in Lower Grade Glioma (LGG) and Uveal Melanoma (UVM)." (PMID 34055889, 2021). "As a predictor of poor prognosis, CCDC137 was found to be correlated with tumor immunosuppressive status and in lower grade glioma and uveal melanoma, CCDC137 could regulate the high infiltration levels of tumor associated macrophages (TAMs) and cancer associated fibroblasts (CAFs)." (PMID 37064086, 2023). "CCDC137, as one vital member of coiled‐coil domain containing (CCDC) family proteins, was overexpressed and positively associated with worse prognosis in various tumour types, such as liver hepatocellular carcinoma, lower grade glioma and prostate adenocarcinoma." (PMID 36254394, 2022).
hepatocellular carcinoma (3 papers, 2022 to 2024). A malignant tumor that arises from hepatocytes. "The critical proliferation‐related role of CCDC137 was demonstrated in hepatocellular carcinoma (HCC) patients by STAMP." (PMID 39392204, 2024). "However, the expression and clinical significance of the coiled-coil domain-containing 137 (CCDC137) in hepatocellular carcinoma (HCC) have not been investigated." (PMID 36061359, 2022).
HIV-1 infection (3 papers, 2021 to 2023). The type species of lentivirus and the etiologic agent of acquired immunodeficiency syndrome (AIDS). "CCDC137 has been previously reported as a chromosome periphery protein and participates in HIV-1 infection." (PMID 37542342, 2023). "Zhang and Bieniasz identified coiled-coil domain containing 137 (CCDC137) as a target of Vpr that when depleted not only more closely mimicked the HIV-1 infection-triggered Vpr-mediated G2/M cell cycle arrest but also produced the enhanced HIV-1 gene expression, suggesting it is a core Vpr target." (PMID 37882563, 2023). "Indeed, Vpr causes G2 arrest and enhances HIV-1 gene expression in both primary CD4+ T cells and macrophages through the depletion of CCDC137, and a Vpr-mutant that is defective in G2 arrest is not able to augment HIV-1 infection in macrophages." (PMID 34835114, 2021).
prostate adenocarcinoma (2 papers, 2021 to 2022). "While CCDC137 was low expressed in KICH, Acute Myeloid Leukemia (LAML), Prostate adenocarcinoma (PRAD), Skin Cutaneous Melanoma (SKCM), Thyroid carcinoma (THCA)." (PMID 34055889, 2021).
breast carcinoma (1 paper, 2018). "Further investigations of common pRESs discovered that BDH1, CCDC137, and TBC1D10A transcripts contained a single non-synonymous RNA variant that was unique to breast cancer tissue compared to adjacent normal tissue; thus, further clinical validation is required." (PMID 30071094, 2018).
cancer (7 papers, 2018 to 2023). A tumor composed of atypical neoplastic, often pleomorphic cells that invade other tissues. "In detail, we analyzed the expression level, methylation level, copy-number value, mutation status, and prognostic value of CCDC137 in TCGA pan-cancer." (PMID 34055889, 2021). "Recent pan-cancer research revealed that CCDC137 is an oncogene and predicts poor prognosis in most cancer types." (PMID 37542342, 2023). "CCDC137 exhibits abnormal expression in cancers, with elevated expression in tumor tissues compared with that in normal tissues in most cancer types, including HCC." (PMID 37542342, 2023). "A pan-cancer analysis recently reported that CCDC137 plays a crucial role and acts as a prognostic marker in different forms of cancers." (PMID 35938038, 2022). "According to information obtained from TCGA database, the expression of CCDC137 was significantly increased in the majority of kinds of cancers." (PMID 36061359, 2022). "Since protein expression level is the key factor directly affecting molecular function, we further analyzed the protein and protein phosphorylation level of CCDC137 in TCGA pan-cancer using Ualcan database." (PMID 34055889, 2021). "In our study, we examined the CCDC137 mRNA and protein expression levels and prognostic value in pan-cancer using TCGA and GTEx data downloaded from UCSC Xena." (PMID 34055889, 2021). "In this study, we performed a pan-cancer analysis to explore the role of CCDC137 in tumor progression." (PMID 34055889, 2021). "Next, we investigated the prognostic value of CCDC137 in TCGA pan-cancer using Univariate Cox Regression analysis and Kaplan–Meier analysis." (PMID 34055889, 2021). "CCDC137 expression was evaluated in RNA sequence expression profilers of pan-cancer and normal tissues from The Cancer Genome Atlas (TCGA) and Genotype-Tissue Expression (GTEx) database." (PMID 34055889, 2021). "The expression levels of the BDH1 and TBC1D10A genes were downregulated, while the CCDC137 gene was upregulated in cancer tissue compared to adjacent normal tissue." (PMID 30071094, 2018). "The correlations between CCDC137 and cancer immune infiltrates were investigated." (PMID 36061359, 2022). "We first evaluated the mRNA expression of CCDC137 in pan-cancer data of TCGA using TIMER2 database." (PMID 34055889, 2021). "CCDC137 has not been characterized in any cancer, but its depletion via HIV could cause cell cycle arrest." (PMID 35300417, 2022). "Targeting CCDC137 may become a potential treatment for cancer." (PMID 34055889, 2021). "Based on the pRESs, the following amino acid changes were predicted in cancer tissue compared to adjacent normal tissue: K275R in BDH1, Q288E in CCDC137, and D44H in TBC1D10A." (PMID 30071094, 2018). "This study revealed the potential role of CCDC137 in TME and its prognostic value in pan-cancer, which may help explore a new drug target." (PMID 34055889, 2021). "In order to determine whether or not CCDC137 expression was correlated with cancer, we analyzed its levels in a variety of tumors as well as the normal tissues." (PMID 36061359, 2022).
tumor (5 papers, 2021 to 2023). "A high level of CCDC137 has been linked to a tumor's immunosuppressive condition and has the potential to contribute to an increased infiltration of TAMs and CAFs." (PMID 36061359, 2022). "High CCDC137 may contribute to elevated infiltration of TAMs and CAFs and be associated with tumor immunosuppressive status." (PMID 34055889, 2021). "CCDC137 was over-expressed and associated with worse survival status in various tumor types." (PMID 34055889, 2021). "In addition, the associations between CCDC137 and tumor stromal cells, tumor-infiltrating immune cells, and immune related marker genes were investigated." (PMID 34055889, 2021). "In addition, CCDC137 is associated with immune infiltration and tumor progression in HCC." (PMID 37542342, 2023). "After that, we investigated the relationship between the expression of CCDC137 and the clinical stages, and we discovered that a high level of CCDC137 expression was related with an advanced tumor stage and grade." (PMID 36061359, 2022). "To explore the reasons of the high CCDC137 expression in tumor, we evaluated the genetic and epigenetic changes of CCDC137 using TCGA data from cBioPortal." (PMID 34055889, 2021). "Our results revealed that CCDC137 have close relationships with TAMs and CAFs infiltration in most tumor types." (PMID 34055889, 2021). "We found that CCDC137 expression was higher in relative worse tumor stages in BRCA, LUSC, KIRC, KICH, and HNSC." (PMID 34055889, 2021). "The influence of CCDC137 on the prognosis of tumor patients was analyzed using clinical survival data from TCGA." (PMID 34055889, 2021). "In these immunosuppressive marker genes, TGFB1, NECTIN2, LGALS9, LAG3, and IL10RB were significantly correlated with CCDC137 expression in most tumor types." (PMID 34055889, 2021). "Collectively, these data demonstrate that CCDC137 expression is significantly elevated in HCC tumor tissues and suggest that CCDC137 may be an oncogenic factor and a potential predictive factor of poor prognosis in HCC." (PMID 37542342, 2023). "By detecting the mRNA and protein expression levels of CCDC137 in these specimens, we found that CCDC137 expression was increased in most (17/23) HCC tumor tissues compared with that in the surrounding normal tissues, which verified the expression from the databases." (PMID 37542342, 2023). "A high level of CCDC137 expression was related to an advanced tumor stage and grade." (PMID 36061359, 2022). "Our study identified CCDC137 as an oncogene and predictor of worse survival in most tumor types." (PMID 34055889, 2021). "We observed that CCDC137 was significantly correlated with TGFB1 expression in most tumor types including UVM and LGG, which may indicate the potential mechanism of CCDC137 influencing infiltration of TAMs/CAFs." (PMID 34055889, 2021). "In this study, we identified a novel oncogenic RBP, CCDC137, whose expression was elevated in HCC tumor tissues compared with that in adjacent normal hepatic tissues." (PMID 37542342, 2023). "Similarly, we observed that CCDC137 expression was elevated in liver metastatic CRC patients and positively correlated with advanced tumour stages and lymph node metastatic stages of CRC." (PMID 36254394, 2022). "Moreover, the positive correlations between CCDC137 expression and immunosuppressive genes, such as TGFB1, NECTIN2, LGALS9, LAG3, and IL10RB, indicate the key role of CCDC137 in regulating tumor immunology, macrophage polarization, and CAFs formation." (PMID 34055889, 2021). "In addition, the high expression of CCDC137 indicates the immunosuppression status in LGG and UVM, providing a potential drug target for tumor therapy." (PMID 34055889, 2021).
infection (1 paper, 2020). The state of being infected such as from the introduction of a foreign agent such as serum, vaccine, antigenic substance or organism. "Wild-type CCDC137 was depleted following V1/HA-Vpr infection while mutant CCDC137 (L/A 66–70) largely resisted Vpr-induced depletion." (PMID 32538781, 2020). "Infection with V1/sh enabled effective Vpr-independent CCDC137 depletion in infected macrophages." (PMID 32538781, 2020).
CCDC137 also shares sentences with these, for which no sentence is quoted: uveal melanoma (2 papers); acute myeloid leukemia (1); colorectal cancer (1); Pan (1); Skin Cutaneous Melanoma (1); Thyroid carcinoma (1).